LEF1 (lymphoid enhancer binding factor 1)
Diseases named in the same sentence as LEF1 in open-access papers (continued):
Sharing a sentence is not in itself a finding about the gene and the disease.
hematologic malignancies (3 papers, 2014 to 2024). "LEF-1, together with other cis regulatory elements, functions as a key mediator of the Wnt signaling pathway, an evolutionarily conserved signaling pathway whose dysregulation has been associated with tumors, including hematological malignancies." (PMID 39759529, 2024). "Several human hematologic malignancies exhibit abnormal expression of lymphoid enhancer-binding factor 1 (LEF1), a crucial transcription factor of the Wnt/ß-catenin pathway and a member of the LEF/T-cell factor (TCF) family." (PMID 38730609, 2024). "High LEF1 expression has been reported as a prognostic marker in hematologic malignancies." (PMID 24378360, 2014).
kidney disorder (2 papers, 2016 to 2023). A disease involving the kidney. "In this work, we discovered 20 top eccDNA hub genes in which NCAM1, NFATC1, PRKCB, LEF1, PRKAG2, and GRM8 were strongly linked to a variety of kidney disorders." (PMID 36967395, 2023).
blood tumors (1 paper, 2020). "All blood tumor studies measured LEF1 expression in bone marrow samples, while solid tumor studies in tissue samples." (PMID 32856045, 2020). "First, the number of eligible studies was relatively small, which might influence the pooled results, especially larger scale studies are needed to further discuss the correlation between LEF1 expression and the prognosis of blood tumors." (PMID 32856045, 2020). "In addition, plenty of other clinical researches discussed the impact of LEF1 expression on blood tumors." (PMID 32856045, 2020). "Accordingly, these studies showed LEF1’s prognostic value in human blood tumors was controversial." (PMID 32856045, 2020). "The relationship between LEF1 expression and RFS was reported in four articles with a total of 715 patients, all these studies were conducted in patients with blood tumors and reported HRs with 95% CIs of RFS in multivariate analysis." (PMID 32856045, 2020).
colon polyps (1 paper, 2024). "This is the first study analyzing the gene expression of APC, Wnt3A, Wnt5A, BCL9, and LEF1 in the colon polyps vs. adjacent mucosa and vs. normal mucosa from control individuals." (PMID 39200196, 2024).
head and neck tumors (1 paper, 2019). "Among the most impressive differences in TF activity, head and neck tumors display lower activities of FEV, TFAP2B and GATA2 and higher activities of TFEC, LEF1, and MAFB compared to SDHD-null tumors of other anatomical locations." (PMID 31234811, 2019).
neurodegenerative disease (1 paper, 2025). A disorder of the central nervous system characterized by gradual and progressive loss of neural tissue and neurologic function. "Correlation and functional analyses indicated that LEF1 is closely associated with immune inflammation and neurodegenerative diseases." (PMID 40918098, 2025). "Enrichment analysis revealed that LEF1 is associated with genes linked to neurodegenerative diseases, suggesting its regulatory role in neurodegenerative pathways." (PMID 40918098, 2025). "Given our previous analysis indicating a strong association between LEF1 and neurodegenerative diseases, as well as its loss promoting inflammatory responses, we hypothesized that LEF1 might mediate neurodegenerative disease progression by regulating neuroinflammation." (PMID 40918098, 2025). "Our findings suggest that LEF1 may regulate pathways related to immune inflammation and neurodegenerative diseases." (PMID 40918098, 2025).
LEF1 also shares sentences with these, for which no sentence is quoted: Cerebral ischemia (2 papers); heart failure (2); hypertrophic cardiomyopathy (2); MALT lymphoma (2); pilomatricomas (2); squamous cell carcinoma (2); uveitis (2); abdominal aortic aneurysm (1); acinar cell carcinoma (1); adolescent idiopathic scoliosis (1); anaplastic astrocytoma (1); aneurysm (1); angina (1); arrhythmogenic right ventricular cardiomyopathy (1); autoimmune disease (1); B-cell acute lymphoblastic leukemia (1); basal cell nevus syndrome (1); benign ovarian tumours (1); blepharocheilodontic syndrome (1); cardiovascular diseases (1); colorectal (1); craniosynostosis (1); Creutzfeldt Jakob disease (1); cyst (1); depressive disorder (1); diffuse astrocytoma (1); digestive system disorder (1); dilated cardiomyopathy (1); endometrioid endometrial carcinomas (1); Floating-Harbor syndrome (1).
A further 53 diseases each share a sentence with LEF1 in 1 paper.